MPO (myeloperoxidase)
Diseases named in the same sentence as MPO in open-access papers (continued):
Sharing a sentence is not in itself a finding about the gene and the disease.
COVID-19 (continued). "Indeed, in serum of COVID-19 patients various elements of NET have been identified, e.g. citrullinated histone H3 and myeloperoxidase (MPO)." (PMID 35757770, 2022). "The levels of plasma H3Cit and MPO-DNA were significantly higher in COVID-19 patients with VTE than those without." (PMID 36224604, 2022). "MPO-DNA complexes were not increased in COVID-19 subjects relative to healthy controls, and did not change across time or when compared prior to the first IVIG dose versus 5 days later (respectively)." (PMID 36341409, 2022). "Using immunohistochemistry we investigated deposition of complement factors C1q, MASP-2, factor D (CFD), C3c, C3d and C5b-9 as well as myeloperoxidase (MPO) positive neutrophils and SARS-CoV-2 virus particles in lungs and kidneys from 38 patients who died from COVID-19." (PMID 35237273, 2022). "In addition, MPO and ELA levels at hospital admission were also significantly increased among COVID-19 patients who later died." (PMID 34616409, 2021). "The computed data suggested that these MPO and FOS genes may be potential drug targets of luteolin action in treating PC and COVID-19." (PMID 35178029, 2021). "These cells had a significantly high level of MPO, PRTN3, and PADI4 indicating that they could be a major source of the observed increase in blood level of these autoantigens during severe COVID-19." (PMID 34276672, 2021). "Accordingly, fluorescence imaging of isolated COVID-19 LDGs indicated that the majority displayed a non-segmented nuclear morphology and increased cytoplasmic MPO expression, both signs of granulocyte immaturity." (PMID 34228753, 2021). "Blood serum of COVID-19 patients displayed elevated markers indicating NET formation, including citrullinated histone H3 (Cit-H3) and myeloperoxidase-DNA (MPO-DNA), which also was further shown to have activated NET formation in control neutrophils when the COVID-19 sera was applied in vitro." (PMID 34199761, 2021). "Interestingly, MPO and TSHR were increased in both lung autopsies and whole blood of severe COVID-19 patients." (PMID 34276672, 2021). "Interestingly, scRNA-seq unveiled a cluster of immature CD14+ monocytes, with low HLA-DR and expressing MPO, PLAC8, and IL1R2, in the blood of COVID-19 patients and similar cells were reported in sepsis." (PMID 33674591, 2021). "We investigated lymphocyte and dendritic cells subsets, chemokine/cytokine profiles and evaluated the neutrophil activity mediators, myeloperoxidase (MPO), and reactive oxygen species (ROS), in 10 children with COVID-19 and 9 with MIS-C at the time of hospital admission." (PMID 33841438, 2021). "When compared to hospitalized COVID-19 patients breathing room air, COVID-19 patients on mechanical ventilation had significantly higher levels of circulating cell-free DNA and MPO-DNA but not Cit-H3 or neutrophilia." (PMID 34199761, 2021). "Collectively, the evidence here highlights the potential for ET administration to reduce the severity of lung inflammation through the inhibition of pro-inflammatory cytokines, MPO activity, and NETosis, which thereby protects against ARDS and helps prevent a cytokine storm during COVID-19." (PMID 32646061, 2020). "An anti-malarial drug, hydroxychloroquine, was used for mitigating SLE, RA, and COVID-19 by preventing ROS and IL-8 production and TLR-9 expression, although it remains unclear if it can inhibit the NET formation-related functions of PADs, MPO, and NE." (PMID 40733019, 2025). "Moreover, no changes in serum levels of both CCL3 and MPO were detected; neither between groups of COVID-19 patients and HCs nor between the patient groups." (PMID 37283736, 2023). "Analysing a subset of acute and convalescent COVID-19 plasma, 10 from severe and 15 from non-severe COVID-19 cases, and 9 from pre-COVID-19 controls, we determined MPO levels, MPO activity and soluble EG proteins (syndecan-1 and glypican-1) levels by enzyme-linked immunosorbent assay." (PMID 37147421, 2023).
COVID-19 (continued). "Moreover, only IL-6 and MPO remained significantly different between the severe COVID-19 and severe negative groups during the course of illness." (PMID 35453080, 2022). "In addition, a recent study has shown that indirect markers of NETosis, such as cell-free DNA (cf DNA), myeloperoxydase (MPO)-DNA complexes, and citrullinated histone H3, are higher in non-surviving COVID-19 patients than in surviving patients." (PMID 36619613, 2022). "First reports about the role of NET in patients with COVID-19 were already published soon after the onset of the pandemic describing elevated levels of NET markers such as cell-free DNA, citrullinated Histone H3 (citH3), and myeloperoxidase-DNA (MPO-DNA) complexes in the sera of these patients." (PMID 35581387, 2022). "Indeed, immunostaining for MPO, citH3, CD66b, and CD15 unambiguously demonstrates an abundant presence of NETs and NET-generating neutrophils at sites of alveolar damage and intravascular clotting in COVID-19 lungs." (PMID 34367376, 2021). "In this study, we also observed the co-localization of MPO and 4-HNE, as well as 8-OHdG in the lung tissues of deceased COVID-19 patients, indicating that MPO-mediated oxidative stress may also play a crucial role in the lung injury of COVID-19 patients with severe infection." (PMID 36768969, 2023). "The effects of NaCl on MPO may be clinically relevant in less severe presentations as well, as a pilot study using aerosols of electrolyzed saline (so containing HOCl) proved to be highly effective in the treatment and viral clearance of SARS-CoV-2 in ambulatory patients with COVID-19." (PMID 33772626, 2021). "Sera from COVID-19 patients displayed elevated levels of cell-free DNA, myeloperoxidase-DNA complexes, and citrullinated histone H3, suggesting NET formation and raising the possibility that NETs may provide a potential target for intervention in COVID-19 patients." (PMID 32998763, 2020). "However, whether MPO is involved in EG degradation in COVID-19 has not been investigated." (PMID 37147421, 2023). "Among NETs, NE-DNA complexes were not necessarily specific to severe disease manifestations, unlike the MPO-DNA complexes, which are upregulated only in critically ill patients and could be used as a specific biomarker to predict the development of severe disease in COVID-19 infected patients." (PMID 37248708, 2023). "However, whether functional active MPO correlates with severe COVID-19 has not been reported." (PMID 37147421, 2023). "Comparison of the MPO, ADA, CCL22, TNFα, and IL-6 mRNA expression between patients with and without completion of COVID-19 vaccines did not reveal any statistically significant differences." (PMID 36482706, 2023). "While we did not observe elevated levels of MPO or PR3, we identified high MFI anti-BPI antibodies in 6% of COVID-19 patients." (PMID 34521836, 2021). "As NETosis is an important effector function of neutrophils under inflammatory conditions, it was not surprising that MPO and histone 3 (H3), both NET components, levels were found to be elevated in the plasma, tracheal aspirate, and lung biopsies from COVID-19 patients." (PMID 35409152, 2022). "Importantly an increase in serum levels of the neutrophil granule proteins MPO, lactoferrin and elastase in the COVID-19 ARDS patient cohort confirmed a phenotype of enhanced circulating neutrophil degranulation in the COVID-19 ARDS patient cohort, which was not impacted by dexamethasone." (PMID 33997298, 2021).
atherosclerosis (210 papers, 2009 to 2026). A disease characterized by the build-up of fatty material and calcium deposition in the arterial wall resulting in partial or complete occlusion of the arterial lumen. "Yet, MPO has detrimental effects on the cardiovascular system, fosters the development of atherosclerosis, and is a valid risk predictor in patients with acute coronary syndrome and other CVDs." (PMID 40252642, 2025). "The key limitation of their work was that the evidence was associative and did not unequivocally demonstrate the causal role of macrophage-derived MPO in CKD-accelerated atherosclerosis." (PMID 40002748, 2025). "Numerous studies suggest a robust association between MPO and CVDs, such as atherosclerosis, MIR, coronary artery disease, and stroke." (PMID 38275657, 2024). "Elevated MPO levels within the patient serum have been linked to an increased risk of cardiovascular diseases, including heart attacks and atherosclerosis." (PMID 39456241, 2024). "While MPO is a crucial component of the immune system, it has also been associated with inflammatory processes in various diseases, including atherosclerosis." (PMID 38396639, 2024). "MPO is considered a potential biomarker for assessing inflammation and oxidative stress associated with atherosclerosis, and its measurement in blood samples is being explored in clinical research." (PMID 38396639, 2024). "Endothelial dysfunction, which is considered an early marker of atherosclerosis, has been linked to the potential role of MPO." (PMID 38275657, 2024). "Circulating MPO can be regarded as an indicator of high risk in patients with acute coronary syndromes, atherosclerosis, heart failure, hypertension or stroke." (PMID 38137807, 2023). "MPO is associated with cardiovascular disease, atherosclerosis, glomerulonephritis, arthritis, and Alzheimer’s disease." (PMID 36769060, 2023). "Plasma levels of MPO are typically elevated in patients with acute coronary syndromes, and its expression has been positively associated with atherosclerosis progression." (PMID 37737709, 2023). "MPO produces dysfunctional lipoproteins, which are associated with an increased incidence of atherosclerosis, decreased NO availability, endothelial dysfunction, impaired vascular reactivity, and atherosclerotic plaque instability." (PMID 35600966, 2022). "As numerous studies show, reduced PON-1 activity is characteristic in patients with atherosclerosis and is associated with increased myeloperoxidase (MPO) activity, resulting in the formation of dysfunctional HDL particles." (PMID 35955978, 2022). "By oxidizing apolipoprotein A-I in HDLs, MPO causes HDLs to lose their protective functions in atherosclerosis and become pro-inflammatory." (PMID 35624738, 2022). "Selective MPO inhibitors or polymorphisms of the MPO gene are leading to decreased MPO activity, and reduced the risk or progression of atherosclerosis in apoE−/− mice and humans, respectively." (PMID 36297390, 2022). "In recent years, a significant amount of evidence has implicated a role of MPO in the pathogenesis of atherosclerosis." (PMID 36142645, 2022). "Potential candidates for the oxidation of HDL proteins linked to the progression of atherosclerosis are MPO and superoxide anion generated during NOS uncoupling." (PMID 36297390, 2022). "Several studies have found a strong association between MPO and CVDs; that is, elevated MPO is a biomarker for the occurrence and progression of atherosclerosis, coronary heart disease, hypertension, heart failure, and stroke." (PMID 35983482, 2022). "Transgenic overexpression of apolipoprotein A-I (apoA1) has been shown to delay atherosclerosis lesion progression and promote lesion regression in mouse models; however, apoA1 is subject to oxidation by myeloperoxidase (MPO) and loss of function." (PMID 35120132, 2022).
atherosclerosis (continued). "MPO-deficient mice exhibit exaggerated atherosclerosis, but mice with MPO overexpression in the macrophages from a human transgene also exhibit increased atherosclerosis." (PMID 33234591, 2021). "In the atherosclerosis context, MPO is important due to its association with coronary artery diseases and is considered a circulating marker of cardiovascular diseases (CVD)." (PMID 34500696, 2021). "MPO is involved in neutrophil oxidative burst and has been associated with atherosclerosis, the development of unstable plaques and CVD." (PMID 34680168, 2021). "For example, MPO activity and the presence of its oxidative products have been implicated in glomerular injury, atherosclerosis, lung damage in CF and carcinogenesis." (PMID 33959129, 2021). "The pathogenic role of MPO in human atherosclerosis was revealed by the EPIC/Norfolk study on >25,000 healthy individuals, showing the prospective risk of developing symptomatic coronary heart disease positively correlated with baseline MPO levels." (PMID 34440119, 2021). "Superoxide anion and myeloperoxidase are also key compounds that take part in atherosclerosis pathogenesis and associated inflammation." (PMID 32570831, 2020). "Dysregulation of MPO activity is also linked with inflammatory conditions such as atherosclerosis, emphasising a need to understand the roles of the enzyme in greater detail." (PMID 31002727, 2019). "Cardiovascular health and outcomes are tightly linked to cholesterol levels and atherosclerosis development, and MPO can promote lipoprotein oxidation." (PMID 30889221, 2019). "Considering this, it is possible that reduced secretion of MPO, and therefore higher intracellular MPO, is associated with lower MPO-related tissue transmigration and consequently lower incidence of atherosclerosis." (PMID 30300402, 2018). "MPO has been suggested to be a mediator of endothelial dysfunction and atherosclerosis, and elevated levels are associated with the presence of coronary artery disease, and predicts risk in ACS." (PMID 28881821, 2017). "Although these oxidants have an important immune function by killing invading pathogens and preventing bacterial cell growth, the overproduction of MPO-derived oxidants in the vessel wall during chronic inflammation is strongly implicated in atherosclerosis." (PMID 27997605, 2016). "MPO-induced low density lipoprotein (LDL)-oxidation in blood has been suggested as a causative factor in atherosclerosis." (PMID 25698971, 2015). "This was interpreted as a finding that differs from the findings of studies which demonstrated protective effects of deficient levels of MPO in neutrophils from atherosclerosis." (PMID 26719776, 2015). "Other reports also showed that MPO deficiency or low plasma levels of MPO decrease cardiovascular risk in patients strengthening the case that MPO is a key element for oxidative damages in atherosclerosis." (PMID 23983406, 2013). "There are reports that MPO-deficient mice have a significantly increased incidence of inflammation-associated diseases including experimental autoimmune encephalomyelitis, atherosclerosis, and lung inflammation." (PMID 23593274, 2013). "The effect of MPO deficiency on plasma lipid levels and inflammation was previously studied in the context of atherosclerosis." (PMID 23285030, 2012). "Myeloperoxidase has been extensively implicated as a key mediator of inflammatory and redox-dependent processes in atherosclerosis." (PMID 23251382, 2012).
atherosclerosis (continued). "Additionally, Trbv1 was associated with reactive arthritis [S23] and myeloperoxidase‐induced autoimmunity [S24], and Trbv31 was linked to atherosclerosis [S25]." (PMID 40665793, 2025). "In addition, nitrosative stress caused by MPO’s catalytic activity has been linked to endothelial damage and atherosclerosis development." (PMID 40252642, 2025). "In addition, we examined changes in the activity or levels of proteins (PON1, MPO) of HDL that have been implicated in SLE-related atherosclerosis." (PMID 38514392, 2025). "While MPO is considered as a pivotal element of the innate branch of the immune system due to its bactericidal activity, it has been also linked to multiple pathologies, including atherosclerosis." (PMID 39201490, 2024). "While exogenous and circulating MPO has been extensively studied and implicated in the progression of atherosclerosis, the expression of endogenous MPO within endothelial cells and its association with coronary disease remains unclear." (PMID 39456241, 2024). "Recent studies have also implicated MPO in the promotion and progression of atherosclerosis; it has been shown to contribute to the instability of atherosclerotic plaques and impair endothelial function, thereby playing a pathogenic role in atherogenesis and contributing to oxidative stress." (PMID 38383869, 2024). "Paradoxically, MPO-deficient mice exhibited accelerated atherosclerosis." (PMID 38673843, 2024). "In this respect, MPO-derived oxidants have been implicated in the pathogenesis of many diseases characterised by chronic inflammation, including atherosclerosis and cardiovascular disease, renal, liver and gastrointestinal diseases, cancer, rheumatoid arthritis, and neurodegenerative diseases." (PMID 37569455, 2023). "MPO and its oxidative products contribute to the formation of foam cells, the hallmark of early-stage lesion formation in atherosclerosis, by oxidizing low-density lipoproteins and promoting endothelial dysfunction, apoptosis, plaque instability, and subsequent plaque rupture." (PMID 36982778, 2023). "MPO is implicated in the pathophysiology of numerous diseases including atherosclerosis." (PMID 37895374, 2023). "Finally, we have not evaluated some new promising biomarkers of cardiovascular risk prediction and atherosclerosis, such as high-sensitivity C-reactive protein, fibrinogen, matrix metalloproteinases, and myeloperoxidase." (PMID 36939826, 2023). "MPO plasma levels correlate with the risk of atherosclerosis." (PMID 36297390, 2022). "The present study aimed to determine the plasma ANGPTL6 and MPO levels in both obese and diabetic individuals to validate their role in these conditions and to assess any association between MPO levels and the markers of obesity, inflammation, and atherosclerosis." (PMID 32277104, 2020). "MPO has also been implicated in endothelial dysfunction and atherosclerosis." (PMID 31447863, 2019). "Taken together lipid profile, kidney and inflammatory markers CX3CL1 and MPO are associated with rIMT status, which supports our hypothesis that rIMT could serve as a surrogate marker for atherosclerosis." (PMID 28881821, 2017). "MPO is considered as an important risk factor in atherosclerosis." (PMID 27167346, 2016). "In addition, these data become relevant since MPO has been implicated in several pathologies, including atherosclerosis, myocardial infarction, atrial fibrillation, multiple sclerosis, Alzheimer’s disease, lung cancer, and transplant rejection." (PMID 27916942, 2016). "Moreover, in patients undergoing maintenance HD treatment the higher basal serum MPO was associated with inflammation, advanced atherosclerosis, and poorer prognosis." (PMID 27127544, 2016). "There are several studies evaluating the relationship between MPO deficiency and atherosclerosis." (PMID 26719776, 2015).